LAMP1 (lysosome associated membrane protein 1)
Diseases named in the same sentence as LAMP1 in open-access papers (continued):
Sharing a sentence is not in itself a finding about the gene and the disease.
tumor (continued). "LAMP1 (Lysosome-associated membrane protein-1) is a surface cell protein that attacks cancer researchers' interests for a long time, which is involved in migration and invasion functions in metastatic tumor cells at protein level." (PMID 36743215, 2023). "Expressing hTERT and lysosomal-associated membrane protein 1 (LAMP1) in dendritic cells induces an increased degradation of hTERT by lysosomes into small tumor antigenic peptides, which in turn activate downstream Cytotoxic T Lymphocyte (CTL) responses via antigen presentation." (PMID 38111043, 2023). "We found that, first, virtually all tumor-associated MCs had a higher level of LAMP1 expression." (PMID 36012196, 2022). "The lysosomal associated membrane protein 1–encoded (LAMP1-encoded) protein is a member of a membrane glycoprotein family and may play a role in tumor cell metastasis." (PMID 34747369, 2021). "Notably, circ‐LAMP1 in cancerous tissues was linked to number of tumours (P =.003) and TNM stages (P =.013), both significantly." (PMID 33675150, 2021). "Moreover, lysosomal proteins, such as lysosome-associated membrane protein-1 and lysosomal cysteine proteases, are associated with tumor development and progression." (PMID 25888140, 2015). "Coculture with SLAMF7-overexpressing CT26 tumor cells significantly increased CD107a (Lysosomal-associated membrane protein 1, LAMP1) surface expression on DNT, a maker of degranulation, compared to control CT26 cells, indicating that SLAMF7 ligation could promote DNT cell degranulation." (PMID 41168829, 2025). "In addition to tumor cells, LAMP1 expression in TME components such as cancer-associated fibroblasts (CAFs) could indicate the secretion of pro-oncogenic exosomes, which promote cancer cell invasion and metastasis." (PMID 40872517, 2025). "While these are examples of transient processes by which LAMP1 may be briefly displayed on the cell surface under homeostatic conditions, many tumor cells show a persistent increase in surface expression of LAMP1, which has been linked to their ability to evade immune detection and metastasize." (PMID 40545776, 2025). "In addition, FUS–circTBC1D14 SGs can initiate a cascade of SG‐linked proteins to recognize and control the elimination of SGs by recruiting LAMP1 and enhancing lysosome‐associated autophagy flux, thus contributing to the maintenance of cellular homeostasis and promoting tumor progression in TNBC." (PMID 36806670, 2023). "Moreover, our high-resolution deconvolution microscopy study showed for the first time, at the tissue level, the presence of Lysosome-associated membrane glycoprotein 1 (LAMP1)-positive exosomes/multivesicular bodies being trafficked across the membranes of tumor epithelial cells." (PMID 35203558, 2022). "Mechanistically, NFU induced marked lysosomal enlargement selectively in tumor cells and localized predominantly within LAMP-1-positive compartments." (PMID 42120505, 2026). "Tissue microarray showed significantly higher staining for LAMP-1 in tumor tissue compared to normal tissue (3986 ± 2635 vs. 1299 ± 1291, p < 0.001)." (PMID 40872517, 2025). "In vivo, PET imaging with 89Zr-DFO-anti-LAMP1 PET/CT revealed detectable tumor uptake as early as 24 h post-injection." (PMID 40872517, 2025). "In contrast to these single-compartment approaches, LAMP-1 imaging simultaneously captures both tumor cells and key TME elements due to its high expression across these elements." (PMID 40872517, 2025). "Over-sialylation of lysosome-associated membrane protein 1 (LAMP1) leads to increased lysosomal exocytosis of soluble hydrolases and exosomes from tumor cells, thereby promoting cancer cell invasion and metastasis." (PMID 39937175, 2025). "To explore LAMP1 as a novel epithelial cancer biomarker, we leveraged data from TCGA to compare LAMP1 expression levels in tumor versus normal samples across multiple cancer subtypes." (PMID 40872517, 2025).
tumor (continued). "This indicates that tumor immune cells express LAMP1 at approximately four-fold higher levels than normal organs." (PMID 40872517, 2025). "Tumor cell membrane permeabilization showed only a modest 5–7% increase in LAMP1 expression, indicating that a substantial portion of LAMP1 in the tumor is membrane-bound." (PMID 40872517, 2025). "To evaluate the contribution of immune cells to tumor tissue LAMP1 expression, we gated for CD45+ LAMP1+ cell population." (PMID 40872517, 2025). "Consistent with the findings at the cellular level, the oral administration of D-mannose increased the protein levels of TFE3 and Lamp1 in tumor tissues." (PMID 40259886, 2025). "Our analysis revealed that LAMP1 expression was significantly elevated in tumor samples for most cancer types." (PMID 40872517, 2025). "Functional analysis further indicated that silencing LAMP1 resulted in downregulating pathways critical to tumor development, including epithelial–mesenchymal transition (EMT), autophagy, and apoptosis." (PMID 40872517, 2025). "It has been reported that NEU1 modifies the tumor microenvironment and alters the tumor microenvironment by shearing the salivary acid modification of LAMP1, thereby regulating tumor development and drug resistance." (PMID 40221400, 2025). "This dual-targeting capability offers enhanced sensitivity and a more comprehensive characterization of the tumor, positioning LAMP-1 as an imaging biomarker with the potential to improve diagnostic sensitivity in adenocarcinomas." (PMID 40872517, 2025). "Further, we found slightly more TM4SF5 and SLAMF7 in the LAMP1 immunoprecipitates prepared from tumor tissues of TM4SF5-positive patients, compared with those from non-tumor tissues (lanes 3 to 6)." (PMID 39828766, 2025). "Collectively, our integrated single-cell, spatial RNA sequencing, and pan-cancer gene expression analyses provide compelling evidence that LAMP1 is being highly expressed within the tumor cells and TME elements such as MDSCs and CAFs." (PMID 40872517, 2025). "To our knowledge, we were the first to discover that XPR1 can regulate autophagy and tumor immunity and that XPR1 regulates tumor immunity through the lysosomal protein LAMP1." (PMID 40641524, 2025). "Several glycoproteins associated with the lysosomal pathway, including LAMP1, ASAH1, ATP6AP1, and HEXA, exhibited significantly increased levels of specific glycoforms bearing high-mannose glycans in tumor tissue." (PMID 41061966, 2025). "Our results indicated that the colocalization with LC3 and LAMP1 was more increased in the control mouse tumor tissues than in the IL-32γ-overexpressing mouse tissues." (PMID 39519229, 2024). "Immunohistochemistry analysis revealed an increase in both the percentage of LAMP1-positive tumor cells and staining intensity with increasing tumor grade." (PMID 39669571, 2024). "In vitro studies demonstrated optimal cell viability, increased expression of surface CD107a or lysosome-associated membrane protein 1 (LAMP-1) on CAR-NK cells co-cultured with CDH17-positive cancer cells, and enhanced anti-tumor responses." (PMID 39397869, 2024). "The analysis using the TIMER2.0 database revealed differential expression levels of LAMP1 mRNA across various tumor types." (PMID 39669571, 2024). "We also examined the colocalization with LC3 and LAMP1 in the control and IL-32γ-overexpressing mouse tumor tissues through immunofluorescence analysis." (PMID 39519229, 2024). "LAMP1 exhibits tumor-specific variations and distinct mechanisms of action, even within the same tumor type." (PMID 39669571, 2024). "As a downstream target of miR-373, LAMP1 also inhibits tumor migration and invasion when knocked out." (PMID 39669571, 2024). "Hypoxia is a key factor in the pathogenesis of gliomas, which enhances tumor development by increasing the expression of stemness (CD133, SOX-2) and drug resistance markers (TIMP-1, Lamp-1) in tumor cells." (PMID 39768176, 2024).
tumor (continued). "The colocalization with LC3 and LAMP1 increased to a higher extent in the control mouse tumor tissues than in the IL-32γ-overexpressing mouse tumor tissues." (PMID 39519229, 2024). "Clearly, the impact of LAMP1 on patient survival varies depending on the specific tumor type, potentially reflecting its distinct roles within different malignancies." (PMID 39669571, 2024). "Pyrimethamine suppresses STAT3 action in metastatic breast cancer cell lines ex-vivo by reducing tumor growth and invasion and by increasing Lamp1 production in tumour-infiltrating CD8+T lymphocytes." (PMID 37710280, 2023). "While we observed a downregulation of autophagy upon vascular disruption and subsequent local inflammation in BON cells, an upregulation of LC3B, ATG5, and LAMP1 was detected under multi-chemotherapeutic conditions in the NCI-H295R tumor model." (PMID 36980669, 2023). "Clinical studies investigating the effect of LAMP-1 mRNA-loaded DC vaccines in glioblastoma have observed exceptional tumor-specific CD4+ and CD8+ T cell response and extended overall patient survival (Phase I, NCT00626483, NCT00639639; Phase II, NCT02366728)." (PMID 37681880, 2023). "Murine LAMP1 (mLAMP1)—representing the lysosomal status of potentially infiltrated host macrophages into the tumor tissue—remained unchanged." (PMID 36980669, 2023). "The tumor cells maintained high levels of LAMP1 in the plasma membrane as was determined by FACS analysis of cells isolated from individual tumors, and Western blot shows higher levels of LAMP1 and CTSD in cells isolated from tumors formed by LAMP1Hi cells." (PMID 37003503, 2023). "In order to confirm V8‐induced LMP in vivo, tumour tissue immunofluorescence showed LAMP1 and CTSD colocalization were decreased in 10 mg/kg group of V8 treatment." (PMID 36959764, 2023). "The chi-square analysis indicated that the high LAMP1 expression was correlated with the degree of tumor differentiation and metastasis (P=0.014)." (PMID 35145930, 2022). "Compared to B-MF, FOB upregulated numbers of CD4+ T cells but decreased frequency of IL10+ CD4+ T cells and GrB+ and Lamp1+ (cytolytic) CD8+ T cells in the tumor, implying that the two cells support cancer independently and without reversal of B-MF to B cells." (PMID 36104343, 2022). "E-cadherin and LAMP1 exhibited lower values compared to the control tissue; however, Giantin showed a clear tendency of actually increasing in the tumor epithelium compared to the controls." (PMID 35203558, 2022). "LAMP1 expression varied and seemed to be increasing in the tumor stroma, most probably due to the inflammatory infiltrate; however, its epithelial expression varied in an opposite direction." (PMID 35203558, 2022). "In particular, it should be pointed out that MCs adjacent to tumor cells had the maximum expression of LAMP1 in granules." (PMID 36012196, 2022). "LAMP1 showed a clear increase in the tumor stroma in high-grade tumors, however unquantified images only it was not clear what its contribution would be in the epithelia." (PMID 35203558, 2022). "Increased LAMP1 expression is significantly correlated with histological grade (P= 0.014) and tumor metastasis (P=0.014)." (PMID 35145930, 2022). "It has been proposed that the terminal glycan residue, sLeX, on LAMP-1 is involved in cellular adhesion, tumor invasion, and metastasis by binding to E-selectin-expressing endothelial cells." (PMID 35145930, 2022). "High-resolution deconvolution fluorescence imaging also confirmed that E-cadherin colocalizes with the intracytoplasmic vesicle system in both control and tumor tissue, for both LAMP1 and Giantin markers." (PMID 35203558, 2022). "LAMP1 also showed the same tendency, with an even more clear-cut difference between tumor grades (p = 0.021 and between low-grade/high-grade tumors and the control tissue (p = 0.001, p < 0.001)." (PMID 35203558, 2022).
tumor (continued). "Later equal quantity of proteins extracted from the tumor samples were resolved through western blotting for LAMP1 and LC3-II expression." (PMID 35322026, 2022). "Expression levels of markers defining tumor and stromal cells were also assessed by tSNE heatmaps that demonstrated the higher signal intensity of some of the markers (Des, Sma, Sca, Pcam1, Lamp1, and Ki67), specifically in NPE RMS." (PMID 36127469, 2022). "A previous study has demonstrated that the crcRNA circ-LAMP1 is upregulated in CCA tumor tissues and cell lines, and high expression of circ-LAMP1 is associated with poor survival rates." (PMID 34282753, 2021). "Immunohistochemistry determined that YY1 was decreased in the tumours formed from circ‐LAMP1 depleted KMBC cells." (PMID 33675150, 2021). "The reported activity is related to the LAMP-1 level of expression and the tumor model sensitivity to the DM4." (PMID 33724757, 2021). "For instance, one study in breast cancer reports the presence of LAMP2, a LAMP1 homologous protein, at the PM of tumor cells located at the invasive front." (PMID 33718382, 2021). "We cultured REP-TILs with single-cell suspensions of autologous tumour cells and assessed T cell granulation by using anti-CD107a (LAMP1)." (PMID 34503115, 2021). "As reported by a previous work that M2 macrophage polarization is associated with the hypoxia TME and thus promotes tumor growth, we further uncover the specific molecules involved in these processes, including NRP1/NRP2 and LAMP1 expressed on TAMs." (PMID 34676217, 2021). "Unsurprisingly, increased expression levels of LAMP1 have been correlated with tumor grade, metastatic potential and poor prognosis in many cancers, including breast and colon carcinoma, high grade glioma, and metastatic melanoma." (PMID 33718382, 2021). "The tumour progression‐promoting effect of circ‐LAMP1 was also confirmed in T‐cell lymphoblastic lymphoma previously." (PMID 33675150, 2021). "The higher expression of FAM3C, LGALS9, ANXA1, SPP1, CD99 and LAMP1 in tumor tissues compared with normal tissues were confirmed by immunohistochemistry in tumors." (PMID 35087839, 2021). "GRNVAC1 is a DC-based tumor vaccine and generated through the transfection of mature DCs with TERT mRNA and lysosomal associated membrane protein 1 (LAMP1)." (PMID 32674474, 2020). "Immunostaining of the lysosomal marker LAMP1 was performed on tumor sections from short-term refametinib-treated mouse PDAC tumors equally showed an overexpression of the LAMP1 gene product upon MEKi treatment." (PMID 32194992, 2020). "Machado and colleagues also described that lysosomal exocytosis, which is also mainly mediated by LAMP-1, plays a primary role in tumour progression and chemoresistance." (PMID 33318498, 2020). "By immunizing mice with patient-derived xenograft (PDX) from a colon cancer patient and screening for antibodies specifically staining tumor plasma membrane, we have previously identified several anti-LAMP1 antibodies." (PMID 32673351, 2020). "Since tumor cell lines and PDXs express LAMP1 with different glycan composition, making certain epitopes more or less accessible, these results suggest that different epitopes are accessible on tumor cell lines and PDXs for mAbs derived from the 2 platforms." (PMID 32673351, 2020). "To test cytotoxic capacity of T and NK cell populations, we examined the degranulation response of these cells by analyzing cell surface expression of CD107a/LAMP1 in tumor-infiltrating T and NK cells." (PMID 32680985, 2020). "VP-autofluorescence was also detectable in the lysosomal compartment within the PDX tumor cryosections, where indeed the SF/VP-treated animals showed a decrease of intra-tumoral accumulation of LAMP-1." (PMID 31582741, 2019). "Increased intracellular levels of GZMB and higher levels of extracellular LAMP1 (CD107a) in tumor-infiltrated CD8+ T cells indicate better targeting and killing capacity of cancer cells by CTLs." (PMID 31710308, 2019).
tumor (continued). "Lysosomal exocytosis, by which lysosomes are docked to the plasma membrane in a LAMP1 dependent manner, has been reported to play an important role in the release of exosomes in tumor cells." (PMID 31391477, 2019). "They display phoshatidylserine on the outer membrane and markers such as CD63, CD81, CD9, TSG10 (Tumour Susceptibility Gene 10), and LAMP1 (Lysosomal-Associated Membrane Protein 1)." (PMID 29642618, 2018). "The first of these assays was a CD107a T cell degranulation assay, in which lysosomal-associated membrane glycoproteins (i.e. CD107a or LAMP-1), migrated to the cell surface at the T cell/tumor cell synapse and facilitated cytolytic activity." (PMID 30563566, 2018). "In this experiment, we demonstrated that tumor cell debris (Red) co-localized with LAMP1 (Blue) within the macrophage vesicles corroborating their phagosome-related identity." (PMID 28403150, 2017). "Lysosome associated membrane glycoprotein 1 (LAMP1) and Lysosome associated membrane glycoprotein 2 (LAMP2), which implicates in tumor cell metastasis, were identified with 12 and 9 N-glycosites separately." (PMID 28077793, 2017). "In agreement with above cell culture findings, RBM5 overexpression in tumor xenografts induced LC-3 and LAMP1 localization, indicating that RBM5 induced autophagic flux in vivo." (PMID 26923134, 2016). "The stimulation process induced HBV-specific T cells that possessed a cytolytic phenotype on the basis of LAMP1 staining, consistent with our murine tumor protection data suggesting that GS-4774 elicits in vivo cytolytic activity." (PMID 25051027, 2014). "In this assay, we evaluated the production of multiple cytokines (IFNα, TNFγ, and IL-2) and upregulation of LAMP-1 (CD107a) by tumor- (Melan-A/MART-1) specific T-cells." (PMID 24195078, 2013). "Their study revealed that patients with tumors with high LAMP-1 mRNA expression lived significantly longer after tumor resection than patients with tumors with low to moderate LAMP-1 mRNA levels." (PMID 23372690, 2013). "Lysosome-associated membrane glycoprotein 1 (LAMP1) is a receptor for galectin-3, and was found on the cell surface of highly metastatic tumor cells." (PMID 20831833, 2010). "In addition, the up-regulation of C1qb, C1qa, Lamp1, Lgals3, Gm2a, Gusb, Bax, and other genes helps to enhance the anti-tumor and anti-infection ability of the immune system." (PMID 40767963, 2025). "However, the liver tissues of a patient with insignificantly changed TM4SF5 expression (i.e., TM4SF5-independent) showed less SLAMF7 in the LAMP1 immunoprecipitates from tumor tissue compared with that from non-tumor tissue (lanes 1 to 2)." (PMID 39828766, 2025). "Moreover, the expression of LAMP1 on tumor cells facilitates their interaction with MDSCs, potentially enhancing the immunosuppressive environment that tumors exploit to evade immune detection." (PMID 40872517, 2025). "In addition, we examined the protein levels of TFE3 and Lamp1 (the lysosomal biogenesis-related gene) in tumor tissues via western blot analysis." (PMID 40259886, 2025). "CD45+ immune cells comprised 21.8% of the total LAMP1+ cells within the tumor." (PMID 40872517, 2025). "LAMP1, initially characterized as a structural component essential for lysosomal integrity, is involved in processes such as lysosomal exocytosis and modulation of tumor cell–extracellular matrix (ECM) interactions." (PMID 40872517, 2025). "Lysosomal-associated membrane protein 1 (LAMP-1) and Lysosomal-associated membrane protein 2 (LAMP-2), for instance, are highly glycosylated proteins that are often overexpressed on the surface of invasive tumor cells." (PMID 41373734, 2025). "Notably, co-expression analysis of LAMP1 with tumor markers CD74 and CD68 revealed that LAMP1 expression is mainly located within the tumoral area, potentially representing cancer cells, CAFs, and MDSCs." (PMID 40872517, 2025).